LINC01337 (long independently transcribed non-coding RNA 1337)
Synonyms: TCONS_00009713
Gene: Long non-coding RNA gene on chromosome 5 (80,608,623 to 80,622,524, reverse strand). Ensembl gene ENSG00000251221.
Diseases named in the same sentence as LINC01337 in open-access papers:
LINC01337 is named in the same sentence as 1 disease in open-access papers, as found by Europe PMC text mining. Sharing a sentence is not in itself a finding about the gene and the disease. The quoted sentences say what the papers report.
Huntington disease (1 paper, 2026). Huntington disease (HD) is a rare neurodegenerative disorder of the central nervous system characterized by unwanted choreatic movements, behavioral and psychiatric disturbances and dementia. "LINC01337 is a long intergenic non-protein coding RNA that was reportedly involved with gene variants associated with Huntington’s disease progression according to the GWAS Catalog database." (PMID 41537925, 2026).